RNU6ATAC39P (RNA, U6atac small nuclear 39, pseudogene)
Gene: Small nuclear RNA gene on chromosome 10 (12,456,483 to 12,456,631, forward strand). Ensembl gene ENSG00000252118.
Homologues: Orthologues: chimpanzee RNU6ATAC39P (99% identical), dog RNU6ATAC39P (56% identical). Paralogues in human: RNU6ATAC (50% identical), RNU6ATAC7P (49% identical), RNU6ATAC27P (47% identical), RNU6ATAC21P (46% identical), RNU6ATAC6P (46% identical), RNU6ATAC8P (45% identical), RNU6ATAC41P (44% identical), RNU6ATAC19P (39% identical), RNU6ATAC22P (37% identical).